SIRT2 (sirtuin 2)
Diseases named in the same sentence as SIRT2 in open-access papers (continued):
Sharing a sentence is not in itself a finding about the gene and the disease.
melanoma (continued). "Karwaciak and colleagues demonstrated that the SIRT2 inhibitor AC-93253 inhibits the expression of genes involved in the progression and chemoresistance of melanoma, influencing proliferation and apoptosis." (PMID 33028392, 2020). "We also report here for the first time a possible role of SIRT2 expression levels on the overall survival of melanoma patients." (PMID 33028392, 2020). "Dysregulated SIRT2 expression has been observed in multiple other cancers with clear clinical relevance, including renal cell carcinoma (RCC), gastric cancer, and melanoma, while SIRT2 appears downregulated in ovarian carcinoma and prostate cancer." (PMID 33014852, 2020). "The observed inhibitory effect of NAM on SIRT2 enzymatic activity confirmed previous evidence; we show here that SIRT2 expression is significantly increased in melanoma and inversely related to melanoma-patients survival." (PMID 33028392, 2020). "SIRT2 has been found at higher levels in tissues from lymph node metastases compared to primary melanomas and contributes to melanomas resistance against multikinase inhibitor Dasatinib." (PMID 33178616, 2020). "Altogether these data indicate that SIRT2 expression is increased in melanoma and patients with lower expression show improved survival." (PMID 33028392, 2020). "Our study provides evidence that SIRT2 is one factor responsible for the resistance of melanoma cells to dasatinib." (PMID 31091806, 2019). "Among genes that were upregulated by SIRT2 silencing were those that are downregulated in aggressive melanoma cells (e.g., MGST1 is upregulated in the SSW30 and SSM15 clones)." (PMID 31091806, 2019). "In conclusion, our results show for the first time that SIRT2 is an important regulator of the basic functions and genes of melanoma cells, including those involved in cell motility, proliferation and drug resistance." (PMID 31091806, 2019). "Using in vitro melanoma cell line-based screening, we previously identified an inhibitor of SIRT2, AC-93253, as a compound that downregulates the expression of genes involved in melanoma progression and chemoresistance acquisition." (PMID 31091806, 2019). "We next investigated the effects of the combination of SIRT2 knockout and dasatinib treatment on the migratory function of melanoma cells using the scratch assay." (PMID 31091806, 2019). "Although we did not observe the intrinsic phosphorylation of EGFR in any cell line, the differences in the response of the melanoma cells with SIRT2-downregulation to EGF was evident." (PMID 31091806, 2019). "To characterize the role of SIRT2 in melanoma cells, we downregulated the expression of this gene in two human melanoma cell lines: WM853 and MDA-MB-435S." (PMID 31091806, 2019). "We found that downregulation of SIRT2 drastically altered the gene expression profiles of melanoma cells and sensitized them to dasatinib, suggesting a potential role for SIRT2 in the melanoma therapy failures of this drug." (PMID 31091806, 2019). "We created melanoma cell lines with downregulated SIRT2 expression in the early and metastatic phases and examined their gene expression and resistance to dasatinib treatment." (PMID 31091806, 2019). "As a consequence of this finding, to improve therapeutic potential of present regiments against melanoma, inhibition of sirtuin 2 activity should be considered." (PMID 31091806, 2019). "SIRT2 knockdown in the melanoma cell lines MDA-MB-435S and WM853 sensitized them to dasatinib." (PMID 38369747, 2024). "Notably, an improvement in dasatinib sensitivity had been reported in melanoma cell lines with SIRT2 knockdown." (PMID 38369747, 2024). "Pharmacological inhibition of SIRT2 potentiates NK cell-dependent antitumor immunity and the growth of allograft melanoma, which might be of translational implication in increasing the efficacy of immunotherapy." (PMID 35693795, 2022).
melanoma (continued). "The present study shows that inhibition of SIRT2 (shRNA-mediated knockdown and pharmacological by thiomyristoyl) resulted in sensitization of melanoma cells to the widely used anticancer drug cisplatin, most likely by targeting EGFR stability and downstream signaling." (PMID 34068624, 2021). "Thus, our results show that sirtuin 2 inhibition increased the in vitro efficacy of cisplatin against melanoma cells." (PMID 34068624, 2021). "The consequence of our study is that targeting SIRT2 (with specific inhibitors) may potentially increase the efficacy of cisplatin in regimens currently used for melanoma management." (PMID 34068624, 2021). "Interestingly, the number of NK cells found within melanoma tumors was significantly decreased in Sirt2-KI mice compared to those harvested from WT mice in terms of percentage of total leukocytes (P = 0.0371) and absolute numbers." (PMID 34155309, 2021). "Intriguingly, SIRT2 is also known to contribute in melanoma progression." (PMID 33937086, 2021). "Our findings illustrate the novel capacity of SIRT2 to enhance subcutaneous melanoma progression while raising the vital question of at what point does SIRT2, a tumor suppressor protein that promotes genomic integrity in healthy cells, transition into what can only be described as a tumor promoter." (PMID 34155309, 2021). "In conclusion, our study, and others, suggest that SIRT2 is a tumor promoter in melanoma cells and this sirtuin is a promising target in antimelanoma therapy; these levels may influence the overall survival of melanoma patients." (PMID 34068624, 2021). "After establishing a relationship between NK cell suppression and SIRT2-mediated melanoma growth, we hypothesized that pharmacological inhibition of SIRT2 function in vivo would have a therapeutic effect on tumor progression." (PMID 34155309, 2021). "Furthermore, SIRT2 shows the highest expression value in 8 melanoma cell lines (including SK-MEL-28) as compared to several other cancer lines." (PMID 33028392, 2020). "SIRT2 is a promising target; thus, we downregulated SIRT2 expression in melanoma cells in vertical growth and metastatic phases and demonstrated that sirtuin acts as regulator of the basic functions of melanoma cells." (PMID 31091806, 2019). "In the metastatic melanoma line, inhibition of SIRT2 expression had a slightly reduced effect on colony formation in the control-treated cells, and treatment with dasatinib had much smaller effect on colony formation in the SIRT2-deficient cell line than in the P/VG line." (PMID 31091806, 2019). "To assess whether the genes identified in the RNA-seq analysis were subject to expression changes in other melanoma cells when SIRT2 was inhibited, we treated A375 cells (stage: metastasis) with the SIRT2 inhibitor thiomyristoyl." (PMID 31091806, 2019). "Interestingly, an shRNA screen identified that SIRT2 depletion conferred resistance to vemurafenib in BRAFV600E melanoma cells." (PMID 30143629, 2018). "To examine whether the NK cell is indeed the key immune cell through which SIRT2 affects melanoma growth, we artificially inhibited NK cell function through antibody-mediated NK cell depletion to recreate suppressed NK cell in melanoma TME observed in SIRT2-overexpressing mice." (PMID 34155309, 2021). "Our transcriptomic analysis showed that loss of SIRT2 in both P/VG and metastatic melanoma cell lines was associated with decreased expression of EGFR and EPHA2, receptors that are important for the development, proliferation and acquisition of multidrug resistance by melanoma cells." (PMID 31091806, 2019). "Thus, we created melanoma cell lines with silenced SIRT2 expression." (PMID 31091806, 2019). "Our previous studies using the SIRT2 inhibitor have shown that SIRT2 might be involved in intracellular processes that mediate melanoma proliferation and multidrug resistance, prompting us to further investigate the role of this deacetylase in the biology of melanoma cells." (PMID 31091806, 2019).
melanoma (continued). "Most studies of sirtuin functions in melanoma have concentrated on SIRT1; however, our group and others have also demonstrated the possible involvement of SIRT2 in the multidrug resistance of melanomas." (PMID 31091806, 2019). "As expected, inhibition of sirtuin 2 activities resulted in a decrease in EGFR levels, confirming our previous observation that this sirtuin regulates EGFR gene expression in melanoma cells." (PMID 34068624, 2021). "Interestingly, the expression of SIRT2 protein was substantially increased in the SCM1 clone by cisplatin, indicating that this protein can play a prominent role in the drug resistance of melanoma cells to this drug." (PMID 34068624, 2021). "With this, we conclude that systemic, rather than intra-tumor, SIRT2 expression positively correlates with murine melanoma tumor progression." (PMID 34155309, 2021). "On the other hand, anti-AsGM1 antibody treatment in Sirt2-KI mice did not significantly affect the progression of allograft melanoma tumors which have already decreased infiltrating NK cells." (PMID 34155309, 2021). "The EC50 of NAM on SIRT2 activity in vitro was measured here at 2 μM, suggesting that NAM anti-melanoma activity may be related, at least in part, to the SIRT2 inhibition." (PMID 33028392, 2020). "We provide new tools in the form of cell lines lacking SIRT2 expression to study the role of this sirtuin in melanoma cells." (PMID 31091806, 2019). "Our results showed that lack of SIRT2 expression in the P/VG melanoma line significantly inhibited cell motility by 4.5-fold (24 h) to 470-fold (48 h), and treatment with dasatinib strongly increased the observed inhibitory effects of SIRT2 depletion." (PMID 31091806, 2019). "Consistently, protein but not mRNA levels of SIRT2, USP22, and PD- L1 positively correlate in human bladder cancer and melanoma." (PMID 42228402, 2026).
neuroblastoma (19 papers, 2008 to 2025). Neuroblastoma (NB) is the most common solid, extracranial childhood tumor. "Transcriptional upregulation of SIRT2 by the HDAC inhibitor trichostatin A in neuroblastoma cell lines had been linked to hyperacetylation of the DNA-bound histone H4 in the SIRT2 promoter region." (PMID 38369747, 2024). "These authors further confirmed upregulation of SIRT2 at 12 and 24 hr in mouse neuroblastoma cells Neuro-2a in response to the HDAC inhibitors vorinostat, apicidin, and M344." (PMID 38369747, 2024). "The class III histone deacetylase SIRT2 is upregulated by N-Myc in neuroblastoma cells and by c-Myc in pancreatic cancer cells, and SIRT2 enhances N-Myc and c-Myc protein stability and promotes cancer cell proliferation." (PMID 37779142, 2023). "In human neuroblastoma cells, autophagic flux was inhibited upon SIRT2 overexpression, as evidenced by increased accumulation of LC3-II and p62 proteins." (PMID 35008169, 2021). "In the same experimental model, SIRT2 overexpression interfered with the accumulation of autophagosomes following proteasome inhibition, leading to neuroblastoma cell death." (PMID 35008169, 2021). "In an Affymetrix gene array study in human neuroblastoma cells 30 h after transfection with scrambled control siRNA or SIRT2 siRNA-1, the gene most notably reactivated by SIRT2 siRNA-1 was NEDD4-1." (PMID 31787758, 2019). "P38 was proved to be one of SIRT2 substrates, SIRT2 deacetylated P38 to suppress neuroblastoma." (PMID 37215138, 2023). "While most of the miRNA regulated molecules that we studied were associated with apoptosis, we did include other molecules such as SIRT2 because SIRT2 was shown to be upregulated by N-Myc in neuroblastoma cells and that SIRT2 promoted cancer cell proliferation." (PMID 30713602, 2019). "As observed in CGNs, SIRT2 overexpression had an apoptotic effect on untreated neuroblastoma cells." (PMID 19116652, 2008). "SIRT2 serves as an efficient “eraser” of multiple histone lactylation sites, targeting synthetic histone peptides, purified histones, nucleosomes, and histones in neuroblastoma (NB) cells." (PMID 40226593, 2025). "A feedback interaction is also described between SIRT2 and N-MYC in neuroblastoma cells, and with c-MYC in pancreatic cancer cells." (PMID 30761005, 2019). "Downregulation of Sirt-2 reduces MYCN gene expression and results in apoptosis in a neuroblastoma cell line." (PMID 30713602, 2019). "In leukemia, neuroblastoma, HCC, and pancreatic cancer, SIRT2 gene is upregulated and is responsible for vascular invasion, cell proliferation, and tumor growth." (PMID 30761005, 2019). "SIRT2 acts as a tumor suppressor and an oncogene; it interacts with β-catenin and lysine-specific demethylase 4A (KDM4A) to inhibit cell growth, and is involved in survival and cell proliferation in pancreatic cancer, hepatocarcinoma, and neuroblastoma." (PMID 35054489, 2022). "We next examined whether the effects observed with SIRT1, SIRT2, SIRT3, SIRT5, and SIRT6 on the regulation of LK-induced neuronal death extended to mouse HT-22 cells, a hippocampally-derived neuroblastoma cell line." (PMID 19116652, 2008).
pancreatic cancer (19 papers, 2011 to 2026). "As mentioned, we have shown that Sirt2 knockout mice with a KRASG12D mutation background develop pancreatic cancer, suggesting Sirt2 knockout is susceptible for pancreatic cancer." (PMID 30405152, 2018). "If the decrease in SIRT2 activity in the pancreas accelerates the accumulation of oncogenic Kras mutations, it seems reasonable to propose that caerulein-induced pancreatitis in Sirt2−/− mice would be a useful model system for spontaneous Kras mutation-initiated pancreatic cancer in humans." (PMID 30405152, 2018). "Conversely, lysine acetylation inversely regulates LDHA: K5 deacetylation by SIRT2 activates and stabilizes it in pancreatic cancer, while K5 acetylation triggers lysosomal degradation." (PMID 41454479, 2026). "For instance, SIRT1 and SIRT7 were reported to promote pancreatic cancer progression, while SIRT2, SIRT4, SIRT5, and SIRT6 seem to play a tumor suppressor role." (PMID 41391757, 2025). "Further supporting the critical role of SIRT2 in pancreatic cancer, recent computational screenings have identified fluvastatin sodium as another potent inhibitor of SIRT2." (PMID 39682281, 2024). "Like SirReal2, NDP11033 decreased BubR1 protein levels in the PANC-1 pancreatic cancer cell line, consistent with on-target cellular Sirt2 inhibition." (PMID 38474697, 2024). "The suppression of SIRT2 activity by fluvastatin sodium offers a new avenue for therapeutic intervention, highlighting SIRT2 as a pivotal regulator of tumor progression and presenting a novel strategy for the targeted treatment of pancreatic cancer." (PMID 39682281, 2024). "Given their ability to impair tumor cell proliferation by modulating the acetylation of critical substrates like eIF5A, SIRT2 inhibitors represent a novel avenue for pancreatic cancer therapy." (PMID 39682281, 2024). "Experimental validation through Western blotting and enzyme inhibition assays confirmed fluvastatin sodium’s potential to suppress pancreatic cancer metastasis by targeting SIRT2." (PMID 39682281, 2024). "SIRT2 exerts significant influence on pancreatic cancer carcinogenesis by intricately regulating KRAS activity and its downstream oncogenic pathways." (PMID 39682281, 2024). "In pancreatic cancer cells, SIRT2 is upregulated by c-Myc, subsequently enhancing the stability of Myc proteins and promoting cancer cell proliferation." (PMID 39682281, 2024). "Second, HDAC6- and SIRT2-mediated deacetylation of KRASMut lysine 104 increases the survival of KRASMut pancreatic cancer cells." (PMID 37779142, 2023). "On the other hand, enhanced c-MYC protein stability by NAD-dependent deacetylase sirtuin-2 (SIRT2) or inhibitor of nuclear factor kappa B kinase subunit epsilon (IKKε) has been demonstrated to increase pancreatic cancer tumorigenicity." (PMID 28383487, 2017). "Several studies have shown that inhibition of Sirt1 and Sirt2 in human pancreatic cancer cell lines can significantly inhibit cell proliferation and induce apoptosis." (PMID 25051362, 2014). "Since Sirts regulate tumor formation and angiogenesis, we next examined the effects of resveratrol on the expression of Sirt1, Sirt2 and Sirt3 in pancreatic cancer cells by q-RT-PCR." (PMID 21980390, 2011). "Accumulating evidence suggests that SIRT2 might be a critical modulator in the carcinogenesis of pancreatic cancer, particularly through its aberrant expression in both benign and malignant tissues." (PMID 39682281, 2024). "NDP11033 and SirReal2 also reduced PANC-1 cell viability, suggesting that targeted Sirt2 inhibition via the ‘selectivity pocket’ may be beneficial in pancreatic cancer." (PMID 38474697, 2024). "Even in pancreatic cancer, the precise role of SIRT2 remains elusive and opposite." (PMID 38216561, 2024).
pancreatic cancer (continued). "By stabilizing interactions with key residues, NPD11033 not only inhibits the deacetylase activity of SIRT2 but also impairs the proliferation of pancreatic cancer cells, as evidenced by the increased acetylation of its physiological substrate, eukaryotic translation initiation factor 5A (eIF5A)." (PMID 39682281, 2024). "Additionally, lysine 147 was discovered to be a novel substrate for SIRT2-mediated deacetylation, and its acetylation status strongly affects the oncogenic properties of KRASMut pancreatic cancer cells." (PMID 37779142, 2023). "In addition, it has been reported that histone deacetylase 6 (HDAC6) and SIRT2 deacetylate KRASMut at lysine 104 to increase the survival of KRASMut pancreatic cancer cells." (PMID 37779142, 2023). "Also, SIRT2 has been shown to be involved in the inflammatory response, and pancreatic inflammation is a key issue in pancreatic cancer incidents in humans." (PMID 30405152, 2018). "Similarly, another study underscores SIRT2’s critical role in modulating inflammatory responses and tissue recovery, highlighting its involvement in creating a microenvironment conducive to the development and progression of pancreatic cancer." (PMID 39682281, 2024). "In addition, SIRT2-induced c-Myc stabilization promotes pancreatic cancer cell proliferation." (PMID 34650436, 2021). "The inhibition of SIRT2 with small molecules reverses these effects by reactivating NEDD4 expression, promoting Myc degradation and suppressing pancreatic cancer proliferation." (PMID 39682281, 2024). "In PANC-1 pancreatic cancer cells, NPD11033 not only decreased cell proliferation but also increased the acetylation level of eIF5a, a SIRT2 deacetylation substrate." (PMID 34650436, 2021). "In the present study, resveratrol inhibited the expression of SIRT1, SIRT2 and SIRT3 in pancreatic cancer cells, thus suggesting a role of SIRT1 as a tumor suppressor in cancer cells." (PMID 21980390, 2011). "SIRT2, though less studied in pancreatic cancer, has emerged as a potential therapeutic target with the discovery of NPD11033, a selective small-molecule inhibitor that induces a conformational change in SIRT2, inhibiting its activity." (PMID 39682281, 2024). "Mice lacking Sirt2 spontaneously develop tumors in multiple organs, as well as when expressed in combination with oncogenic KrasG12D, leading to pancreatic tumors." (PMID 30405152, 2018). "While the roles of SIRT2, SIRT4, and SIRT5 in pancreatic cancer progression are evident, their utility as biomarkers is not yet fully established." (PMID 39682281, 2024).